SOX17 (SRY-box transcription factor 17)
Diseases named in the same sentence as SOX17 in open-access papers (continued):
Sharing a sentence is not in itself a finding about the gene and the disease.
congenital heart disease (4 papers, 2018 to 2024). A heart disease that is present at birth. "A whole exome sequencing study involving 256 patients with PAH strongly implicated SOX17 pathogenic variants as a major risk factor in PAH-associated congenital heart disease and also provided independent validation for their role in IPAH." (PMID 37895315, 2023). "Research conducted on PAH associated with congenital heart disease (CHD) indicated that variants in SOX17 might be particularly prevalent in this subgroup, as two out of our seven additional patients presented with CHD." (PMID 37895315, 2023). "For example, variants in the endoglin gene are linked with PAH associated with connective tissue disease, polymorphisms in estrogen-related genes may impact the risk of portopulmonary hypertension, and SOX17 have been implicated in PAH associated with congenital heart disease." (PMID 33996849, 2021). "Research conducted on a group of PAH patients with congenital heart disease indicated that SOX17 variations are particularly prevalent in this subgroup, which experiences an early onset of the disease." (PMID 37895315, 2023). "Interestingly, SOX17 deficiency, a risk factor for the development of IPAH, HPAH and PAH associated with congenital heart disease, was reported to transcriptionally induce DLL4 and protect against vascular leakage." (PMID 38903104, 2024).
pulmonary hypertension (4 papers, 2023 to 2024). Increased pressure within the pulmonary circulation due to lung or heart disorder. "In addition to animal models using conditional deletion of endothelial SOX17, transgenic mice engineered to resemble SOX17 mutations associated with increased risk of PAH are also more susceptible to pulmonary hypertension." (PMID 38028440, 2023).
endometriosis (3 papers, 2018 to 2023). The growth of functional endometrial tissue in anatomic sites outside the uterine body. "This demonstrates that the uterine epithelium expression of SOX17 is conserved between mouse and human, and in the human endometrium SOX17 expression is impacted by endometriosis." (PMID 30356064, 2018). "Here the authors show that SOX17 is upstream of Indian hedgehog to regulate mouse uterine receptivity, and their analysis of uterine tissue from endometriosis patients suggests the same function in humans." (PMID 30356064, 2018). "In addition, ARID1A, a chromatin remodeling complex protein potentially regulated by SOX17, is decreased in endometrium from endometriosis patients." (PMID 31387263, 2019). "Moreover, SOX17 expression is reduced in women with endometriosis, correlating with a drop in IHH expression, which it normally regulates by binding a distal enhancer to promote endometrial receptivity in the healthy endometrium." (PMID 31387263, 2019). "To investigate SOX17 role in human endometrial function, we analyzed its expression pattern in endometrial tissue from women with and without endometriosis at proliferative and secretory phases (n = 7 per phase per disease)." (PMID 30356064, 2018).
glioblastoma (3 papers, 2015 to 2024). The most malignant astrocytic tumor (WHO grade IV). "In human malignant tumors, SOX17 was reported to be predominantly and specifically expressed in TECs in four out of five high‐grade human glioblastoma tissue specimens." (PMID 39385307, 2024). "In pancreatic tumors and glioblastomas, SOX17 has been established as a key regulator of inducing tumorigenesis and promoting tumor angiogenesis." (PMID 29970906, 2018).
infertile (3 papers, 2016 to 2019). "Sox17 is detected in about 10% of all testis specific genes, and Spz1, a spermatogenic Zip regulatory Protein, is drastically reduced in meiotic cells of oligozoospermic infertile men." (PMID 31645906, 2019). "Notably, Sox17+/GFP females had a smaller litter size and tended to become infertile early in adulthood." (PMID 27053385, 2016).
lymph node metastasis (3 papers, 2015 to 2022). "Abnormal SOX17 methylation in cancer tissues and plasma DNA was found to be significantly associated with tumor lymph node metastasis and lymph node metastasis, associated with poor disease-free survival (P < 0.005) and overall survival (P < 0.005)." (PMID 34557230, 2021). "The rate of SOX17 expression was lower among cases with lymph node metastasis than among those without lymph node metastasis (P < 0.05)." (PMID 36072972, 2022).
Right ventricular hypertrophy (3 papers, 2023 to 2025). In this case the right ventricle is more muscular than normal, causing a characteristic boot-shaped (coeur-en-sabot) appearance as seen on anterior- posterior chest x-rays. "The increased levels of RVSP, right ventricular hypertrophy (RV/LV+S), and RV weight/tibial length (RVH) of mice stimulated by Su/hypo were significantly prevented by SOX17‐associated exosomes." (PMID 36919784, 2023). "SOX17 overexpression significantly reduced PH severity, as evidenced by lower right ventricular systolic pressure (RVSP) and reduced right ventricular hypertrophy, consistent with the recovered Nestin levels in lungs (columns 2 and 3)." (PMID 40766215, 2025).
serous 'ovarian' cancer (3 papers, 2020 to 2024). "Depleting SOX17 from human high‐grade serous ovarian carcinoma cells altered the expression of factors involved in angiogenesis and functionally disrupted tubule and capillary formation in cell culture and mouse models." (PMID 39385307, 2024). "SOX17, an important member of SOX family, which encodes an antagonist of Wnt signaling pathway, was found to be frequently methylated in high-grade serous ovarian cancer." (PMID 33135729, 2020). "The transcription factors MECOM, PAX8, SOX17 and WT1 are candidate master regulators of high-grade serous 'ovarian' cancer (HGSC), yet their cooperative role in the hypothesized tissue of origin, the fallopian tube secretory epithelium (FTSEC) is unknown." (PMID 37090516, 2023).
uterine corpus endometrial carcinoma (3 papers, 2019 to 2022). A endometrial carcinoma (disease) that involves the body of uterus. "We observed similar features in the uterine corpus endometrial carcinoma dataset: the genes with the highest frequency included SOX17 and C3 (8%), PAX8, MME and ESR1 (7%)." (PMID 31879572, 2019).
aneurysm (2 papers, 2015 to 2025). Bulging or ballooning in an area of an artery secondary to arterial wall weakening. "Genome-wide association studies have consistently implicated SOX17 among IA susceptibility loci, supporting a causal link between endothelial regulatory networks and aneurysm biology." (PMID 41303289, 2025). "This association has received recent experimental support from studies of mice in which EC-specific deletion of Sox17 combined with pharmacologically-induced chronic hypertension produces cerebrovascular tortuosity, aneurysms, and hemorrhage." (PMID 26630461, 2015). "CRISPR activation (CRISPRa)-mediated upregulation of SOX17 enhanced protective endothelial programs and reduced inflammatory and pro-degenerative signaling in IA models, establishing proof-of-concept for gene-editing–guided aneurysm wall stabilization (preclinical stage as of 2025)." (PMID 41303289, 2025).
arterial hypertension (2 papers, 2019 to 2024). "These signals identified enhancer regions leading tomodified expression of SOX17, which correlated with the diagnosis ofpulmonary arterial hypertension." (PMID 30527955, 2019). "In this study, we focus on the function of Sox17 in AngII induced hypertension model." (PMID 37659973, 2024). "However, the underlying molecular mechanism of how Sox17 alteration affects vascular endothelial cell injury, particularly under hypertension conditions, has not been elucidated." (PMID 37659973, 2024). "In the current study, we used AngII-stimulated human brain microvascular endothelial cells (HBMECs) as a cell model of hypertension to explore the effect of Sox17 on apoptosis and autophagy of HBMECs, which might reveal the underlying molecular mechanisms of how Sox17 affects IA formation." (PMID 37659973, 2024).
diabetes (2 papers, 2014 to 2016). "Consistant with this, Sox17-paLOF mice were more susceptible to aged-related and high fat diet-induced hyperglycemia and diabetes." (PMID 25144761, 2014). "To determine if loss of Sox17 predisposes animals to diabetes progression as they get older, we analyzed these mice at 1.5 years of age." (PMID 25144761, 2014). "Given the predisposition of Sox17-paLOF mice to age related diabetes, we investigated if loss of Sox17 predisposes animals to high-fat diet-induced diabetes." (PMID 25144761, 2014). "Moreover, SOX17 plays a key role in regulating insulin secretion, as mice lacking Sox17 were more susceptible to high fat diet-induced hyperglycemia and diabetes." (PMID 27556491, 2016). "Taken together, these data suggest that Sox17-paLOF mice have β cell dysfunction, are prediabetic, and are prone to high fat diet-induced diabetes." (PMID 25144761, 2014). "Several candidate genes, including SOX17, were investigated for a role in neonatal diabetes mellitus in humans, however no SOX17 mutation were associated with this form of diabetes." (PMID 25144761, 2014). "Together, these data demonstrate a critical new role for SOX17 in regulating insulin trafficking and secretion and that modulation of Sox17-regulated pathways might be used therapeutically to improve cell function in the context of diabetes." (PMID 25144761, 2014). "Our results suggested that absence of Sox17 in adult pancreatic β cells results in mice with prediabetic symptoms including improper secretion of proinsulin, abnormal secretory organelles, and development of diabetes when aged and in response to a high fat diet." (PMID 25144761, 2014).
Endometrial tumors (2 papers, 2016 to 2019). "High SOX17 levels were observed in benign endometrial tumor tissues, with low expression in malignant EC tissues." (PMID 27738313, 2016).
gallstones (2 papers, 2020 to 2025). Solid crystalline precipitates in the biliary tract, usually formed in the gallbladder, resulting in the condition of cholelithiasis. "Therefore, we speculate that gallstones or other physical obstructions that cause inflammation may cause dysplasia and/or metaplastic transformation by altering epithelial Sox17 levels." (PMID 39745200, 2025). "For pathological analysis of human gallbladders, we first examined the SOX17/SOX9 expression profiles in seven non-BA [six congenital biliary dilation (CBD) cases, one gallstone (GS) case] and eight control [one pancreatoblastoma (PB) case, seven hepatoblastoma (HB) cases] gallbladders." (PMID 31996362, 2020).
gynecological cancer (2 papers, 2018 to 2026). "This indicates that the role of Sox17 in the development of cancer of the uterus may be in the modification of a critical regulator of endometrial cell homeostasis." (PMID 30356064, 2018).
Hyperglycemia (2 papers, 2014 to 2016). An increased concentration of glucose in the blood. "However, after 10 days of Sox17 overexpression, we observed broad loss of proinsulin throughout the secretory system correlated with hyperglycemia and an increase of proinsulin in the plasma, suggesting that Sox17 overexpression was causing constitutive secretion of proinsulin." (PMID 25144761, 2014). "Together, these data demonstrate that SOX17 expression stimulates the insulin secretory pathway within 24 hours and that continued expression promoted precocious proinsulin secretion and hyperglycemia." (PMID 25144761, 2014).
intrahepatic cholangiocarcinoma (2 papers, 2023 to 2025). A carcinoma that arises from the intrahepatic bile duct epithelium in any site of the intrahepatic biliary tree. "In intrahepatic cholangiocarcinoma (iCCA), SOX17 has been identified as a transcriptional regulator of TNS4, thereby facilitating tumor growth." (PMID 40858565, 2025).
Sepsis (2 papers, 2022). Sepsis is defined as life-threatening organ dysfunction caused by a dysregulated host response to infection. "In another study of HIF-1α signaling during post-sepsis vascular repair in mouse lungs, promoter analysis identified Sox17 as a reparative transcriptional target of HIF-1α." (PMID 35563731, 2022). "In another study of HIF-1α signaling during post-sepsis vascular repair in mouse lungs, promoter analysis identified Sox17 as a transcriptional target of HIF-1α." (PMID 35053299, 2022).
squamous intraepithelial lesion (2 papers, 2018 to 2020). "Switches of SOX17 and SOX2 expression in the development of squamous metaplasia and squamous intraepithelial lesions of the uterine cervix are associated with viral infection." (PMID 32644288, 2020). "Normal cervices and squamous intraepithelial lesions (SIL) were studied with immunohistochemistry, methylation of SOX17, human papilloma virus (HPV) genotyping, and in situ hybridization." (PMID 32644288, 2020).
testis cancer (2 papers, 2020 to 2022). "To address this, we analyzed the correlation between NANOS1 and NANOS3 with its upstream transcriptional program in human primordial germ cells including transcription factors PRDM1, SOX17, TFAP2C, and PRDM14 expression in testis cancer samples." (PMID 36012673, 2022).
adenocarcinoma in situ (1 paper, 2020). A lesion in which the normally situated glands are partially or completely replaced by atypical cells with malignant characteristics. "SOX17 expression has not been studied in glandular lesions of the uterine cervix like adenocarcinoma in situ (AIS) and invasive adenocarcinomas (AdC), whereas SOX17 promoter CpG island methylation has been reported." (PMID 31444787, 2020).
adenomyosis (1 paper, 2025). The growth of endometrial tissue inside the muscular wall of the uterine corpus. "IHH, as well as its transcription factor, receptor, and target gene (SOX17, PTCH1, and HHIP, respectively), exhibiting spatial expression characteristics, were highly expressed in the invaginating site of adenomyosis." (PMID 40190183, 2025).
anaplastic oligodendroglioma (1 paper, 2016). A WHO grade III oligodendroglioma with focal or diffuse malignant morphologic features (prominent nuclear pleomorphism, mitoses, and increased cellularity). "However, in our study, SOX17 was found methylated in anaplastic oligodendroglioma samples, so we speculate that epigenetic silencing of this gene may function as a factor up-regulating the Wnt pathway or deregulating the cell cycle in these tumors." (PMID 26337424, 2016).
anemia (1 paper, 2023). A reduction in the number of red blood cells, the amount of hemoglobin, and/or the volume of packed red blood cells. "Although our previous study revealed that SOX-17 expression is operated by CX3CR1-mediated PR activation, the action of FKN on SOX-17 protein expression is controversial in anemia, probably due to the altered level of progesterone in a serum-free medium." (PMID 37175630, 2023). "FKN induces the secretion of the receptivity-related cytokines at anemia, which may improve endometrium receptivity via the CX3CR1 and the regulation of the NFκB pathway and by regulating activin, follistatin, and BMP2, as well as PR, SOX-17, PTGER2, and TIMP2." (PMID 37175630, 2023).
Anxiety (1 paper, 2022). Intense feelings of nervousness, tension, or panic often arise in response to interpersonal stresses. "The decrease in amygdala Sox17 expression did not alter locomotion or anxiety-related behavior." (PMID 36371333, 2022).
asthma (1 paper, 2020). "Among the top flow central nodes, several genes, such as SLC39A8, SOX17, and MFAP4 show a direct relationship with asthma and COPD." (PMID 32041952, 2020). "More specifically, it has been found in literature that the expression levels of SLC39A8, SOX17, and MFAP4 might directly affect both asthma and COPD." (PMID 32041952, 2020).
atherosclerosis (1 paper, 2024). A disease characterized by the build-up of fatty material and calcium deposition in the arterial wall resulting in partial or complete occlusion of the arterial lumen. "The marker genes for these clusters were then analyzed using KEGG Enrichment, and Etv2#2 and Sox17-Erg#2 were selected for further investigation based on the enrichment for focal adhesion and fluid shear stress and atherosclerosis." (PMID 38755186, 2024).
breast fibroadenomas (1 paper, 2017). "SOX17 promoter was methylated in 3/29(10.3%) non-cancerous breast tissues, and in 2/9 (22.2%) breast fibroadenomas." (PMID 29069768, 2017).
breast invasive carcinoma (1 paper, 2019). "In breast invasive carcinoma, IRF6 showed the highest rate of alteration (6%) followed by SOX17 and MSR1 (3%)." (PMID 31879572, 2019).
cardiac ischemia (1 paper, 2023). "Our transcriptional data provide evidence that significantly higher levels of hypoxia-related and proangiogenic genes (HIF1a, VEGFA, FGF2, eNOS, SOX17, and LRG1) promote neovascularization at the site of increased cardiac ischemia." (PMID 36371548, 2023).
cervical (1 paper, 2018). "To explore the molecular mechanism by which SOX17 inhibits cervical carcinogenesis, we investigated the mRNA expression levels in three HeLa-SOX17 cell lines and three HeLa-GFP cell lines by microarray analyses." (PMID 29970906, 2018).
cervical intraepithelial neoplasia (1 paper, 2025). "A panel of six methylation markers (ASTN1, DLX1, ITGA4, RXFP3, SOX17, ZNF671; GynTect® assay) has shown promise in diagnosing cervical intraepithelial neoplasia (CIN)." (PMID 40022051, 2025).
cholestasis (1 paper, 2025). Impairment of the bile flow caused by obstruction within the liver, or outside the liver in the bile duct system. "When Sox17 expression falls below ∼50%, as occurs in Sox17Δ50/GFPCre mice, development of the GB and EHBD becomes so impaired that the animals die of BA-induced cholestasis and subsequent hepatic necrosis." (PMID 39745200, 2025).
colorectal adenoma (1 paper, 2024). An adenoma that arises from the colon or rectum. "Research has shown that SOX17 enables immune evasion in early colorectal adenomas and cancers by suppressing interferon-gamma (IFNγ) signaling, thereby reducing the immunogenicity of tumor cells." (PMID 38981872, 2024).
COVID-19 (1 paper, 2021). A disease caused by infection with severe acute respiratory syndrome coronavirus 2. "The results indicated that both PPARγ and PPARα are downregulated, while SOX17 and RUNX1 gets upregulated in COVID-19 patients." (PMID 34407143, 2021).
cystic fibrosis (1 paper, 2024). Autosomal recessive disorder caused by pathogenic variants in the CFTR gene (cystic fibrosis transmembrane conductance regulator), which encodes a chloride and bicarbonate channel expressed in epithelial cells, and follow the diagnosis criteria. "Further, we identified an up-regulation in two EndoMT-related genes in Rtn3-null ENs: Sox17, a developmental transcription factor linked to endothelial-to-fibroblast conversion, and Fxyd5, associated with cystic fibrosis airway epithelia." (PMID 38937317, 2024).
dysplasia (1 paper, 2025). A usually neoplastic transformation of the cell, associated with altered architectural tissue patterns. "Five of the six markers (ASTN1, ITGA4, RXFP3, SOX17, and ZNF671) showed good positivity in vulvar dysplasia but with unexpected high positivity in VLSIL (VIN I) FFPE samples compared to higher dysplasia grades." (PMID 40022051, 2025).
Eisenmenger syndrome (1 paper, 2022). "We found a digenic likely pathogenic variant (ABCC8/ SMAD 1) in a case of coincidental PAH and several thoracic collaterals, a pathogenic variant in BMPR2 in a case of PAH after defect closure, and a pathogenic SOX17 variant in a patient with Eisenmenger syndrome." (PMID 36142358, 2022).
endometrioid tumor (1 paper, 2019). A benign, borderline, or malignant epithelial tumor of the female reproductive system characterized by the presence of glands and/or cysts lined by neoplastic cells that resemble endometrial cells. "ANO1, SOX17, CGNL1, DACH1, RUNDC3B, SH3YL1 and CRISPLD1 were significantly downregulated both in papillary serous tumors and endometrioid tumor." (PMID 30813939, 2019).